CAT (catalase)
Diseases named in the same sentence as CAT in open-access papers (continued):
Sharing a sentence is not in itself a finding about the gene and the disease.
tumor (continued). "In contrast, the rare interaction between 1O2 and the catalase on the surface of tumor cells induces a strong and selective effect, as it triggers an autoamplificatory system that is inherent specifically to malignant cells." (PMID 31558835, 2019). "The interaction of the primary as well as the secondary 1O2 with the catalase on the membrane of tumor cells retains a signature that seems to allow this cell to autoamplify 1O2 generation." (PMID 31558835, 2019). "For PDT experiments (660 nm, 220 mW∙cm−2, 5 min) the tumour growth was significantly inhibited showing that the CAT-PS-ZIF@Mem NPs have a high phototoxicity and that the formation of O2 thanks to decomposition of H2O2 improved PDT efficiency." (PMID 31671658, 2019). "As the expression of membrane-associated catalase of tumor cells is modulated by tumor cell-derived superoxide anions and H2O2, siRNA-mediated knockdown of NOX1 causes strong downmodulation of catalase expression." (PMID 31578342, 2019). "With some molecules of their protective catalase inactivated, these tumor cells allow locally surviving cell-derived, extracellular H2O2 and ONOO─ to form secondary 1O2." (PMID 31578342, 2019). "A key conclusion from these experiments is that tumor cell-generated RONS play the major role in inactivating protective catalase, depleting glutathione and establishing apoptosis-inducing RONS signaling." (PMID 31578342, 2019). "As sustained generation of secondary singlet oxygen by the tumor cells is activated at the site of the imprint, a rapid bystander effect-like spreading of secondary singlet oxygen generation and catalase inactivation within the cell population is thus induced." (PMID 31558835, 2019). "The results showed that SOD, catalase, and GPx were all significantly decreased in the tumor-induced group compared to the normal group." (PMID 30787353, 2019). "Tumor cells solve this problem through attachment of catalase to the membrane and thus generate a high local density of catalase at the site where it is actually needed for their protection." (PMID 31578342, 2019). "At the same time, catalase immobilized on the surface of mSiO2 catalyzed H2O2 to produce O2 at the tumor site." (PMID 31534494, 2019). "In particular, CuZn SOD and catalase expression were enhanced in the skeletal muscle of tumor-bearing animals and, similarly, cancer patients showed increased antioxidant enzyme levels and activity." (PMID 30823492, 2019). "Tumor cells always had low MnSOD activity, usually low Cu/ZnSOD activity, and almost always low catalase activity compared with those of the corresponding normal tissues." (PMID 31781331, 2019). "Once a few tumor cells have had their membrane catalase inactivated, these cells themselves generate large amounts of what we refer to as ‘secondary’ 1O2." (PMID 31578342, 2019). "Tumor cells had low MnSOD activity, usually low Cu/ZnSOD activity, and almost always low catalase activity compared with those of the corresponding tumor-free lung tissues." (PMID 31781331, 2019). "The treatment of tumor cells with CAP or PAM finally results in 1O2-mediated inactivation of catalase to a degree that allows for reactivation of intercellular HOCl signaling." (PMID 31578342, 2019). "The increase in CuZn SOD was coupled with upregulation of catalase levels in exercised C26-bearing mice as compared to both sedentary controls and tumor bearers." (PMID 30823492, 2019). "After 13 days of xenograft growth in vivo, significant decreases in HIF-1α, FoxO1, Sesn3, MnSOD and catalase expression were exhibited by the tumours from the 2ME + As2O3 treatment group compared with the tumours from the control group." (PMID 31905813, 2019). "After modification with catalase and c(RGDyK) as the targeting moiety that specifically recognizes tumor cells, we performed targeted PTT and PDT of tumors in tumor-bearing nude mice." (PMID 31534494, 2019).
tumor (continued). "These relatively brief steps create what we refer to as ‘primary’ singlet oxygen in the liquid medium in relatively small numbers, but they inactivate at least a few of the membrane-bound catalase enzymes of tumor cells in solution." (PMID 31578342, 2019). "This established autoamplificatory 1O2 generation by the tumor cells, catalase inactivation and reactivation of intercellular apoptosis-inducing RONS signaling." (PMID 31558835, 2019). "Antipimonidazole antibody was used to detect hypoxia zones on tumour slices and revealed a large decrease of tumour hypoxia after CAT-THPP-PEG treatment compared to BSA-THPP-PEG treatment." (PMID 31671658, 2019). "In vivo studies in BALB/c mice bearing 4T1 tumours (660 nm, 5 mW∙cm−2, 60 min) confirmed the in vitro studies with a large inhibitory effect of the tumour growth after CAT-THPP-PEG injection." (PMID 31671658, 2019). "Conversely, the mice treated with MeOH, CH2Cl2 and insoluble extracts showed a significant (p < 0.001) elevation in CAT level in relative to that of vehicle control group (tumor + DMSO)." (PMID 31288458, 2019). "Compared to the low concentration of catalase in the total volume of the tumor cells, the high local concentration of catalase on the spatially restricted site of the membrane is not relevant." (PMID 31578342, 2019). "Compared with the control group, LGT administration significantly elevated the MDA level (P<0.01), and reduced GSH, GST, GPx, SOD, and CAT levels (all P<0.01) in hepatic of S180 tumor-bearing mice." (PMID 29950302, 2018). "In order to decrease the effect of H2O2 in the tumor, scientists added the ability of catalase production to the CAR T cells (CAT-CAR)." (PMID 30108584, 2018). "Worthy to notice, in several types of cancer, the ratios MnSOD/catalase and MnSOD/glutathione peroxidase have been suggested as biomarkers for tumor progression and metastasis." (PMID 30042310, 2018). "It would be appropriate to note that IFBO administration curtailed the levels of MDA and PC with restoration of enzymatic antioxidant defense of GSH, SOD and CAT, substantiating its tumor protecting ability with notable antioxidant effects." (PMID 29651140, 2018). "Here, the authors describe a nanoflower where oxidase mimicking PtCo nanoparticles are decorated with catalase mimicking MnO2 to reverse tumor hypoxia and generate reactive oxygen species for dynamic therapy." (PMID 30127408, 2018). "A previous investigation also demonstrated a rise in protein catalase content in the fast-twitch fiber muscles of tumor-bearing rats." (PMID 29255650, 2017). "When these nanoparticles are taken up by the tumor cells, the O2 generated by the catalase from intracellular H2O2 not only facilitates drug release but also be helpful in overcoming hypoxia‐induced MDR which limits the effectiveness of chemotherapy." (PMID 28105390, 2017). "This selectivity appears to be due to the higher catalase content observed in normal cells (∼10-100 fold greater), as compared to tumor cells." (PMID 28978032, 2017). "On the other hand, the majority of tumor cells frequently possess very little antioxidative enzymes such as catalase, superoxide dismutase and glutathione peroxidase that makes tumor cells very vulnerable to oxidative stress." (PMID 27738496, 2016). "This is due to the presence of hypoxic tumor cells and an abundance of antioxidative enzymes, including peroxidase and catalase, in larger tumors." (PMID 26751477, 2016). "It has been demonstrated that enhanced level of GPx alone can prevent oxidative insult in SOD1 and catalase dual suppressed cells, thereby suggesting concordant roles of these three antioxidant enzymes in tumor progression/regression." (PMID 26682000, 2016). "The expression of FOXO1 and its downstream anti-oxidative stress enzymes such as catalase and MnSOD were also at a high level in tumor tissues." (PMID 27566573, 2016).
tumor (continued). "Peroxidases and catalase are abundant in most tumor tissues, as demonstrated by the need to block endogenous peroxidase activity before immunohistochemical staining of fresh tumor tissues." (PMID 26927177, 2016). "Reactive oxygen species (ROS) are highly indicative as one of many causative factors in tumour promotion whereas antioxidants such as GSH, SOD and CAT are indispensable for protection against the deteriorating effects." (PMID 26638207, 2015). "EASA also significantly modulated the hepatic and renal antioxidant parameters, i.e. lipid peroxidation, reduced glutathione level (GSH), activities of superoxide dismutase (SOD) and catalase (CAT) in tumor bearing mice." (PMID 27486371, 2015). "This autoamplification of singlet oxygen through versatile usage of tumor cell specific ROS chemistry finally leads to the inactivation of catalase." (PMID 26225731, 2015). "Within the database, 59 directly matched tumor versus normal tissue samples also showed the same elevated NQO1:Catalase ratio (SF1)." (PMID 26602448, 2015). "Using a current linear accelerator, our intent was to inactivate peroxidase/catalase in tumor tissue by the application of hydrogen peroxide, which is degraded to produce oxygen, thus re-oxygenating the tumor tissue." (PMID 26703733, 2015). "Elevation of enzyme activities like SOD and CAT in EASA treated tumor bearing mice revealed the activation of enzymatic antioxidant defense mechanisms by which EASA resulted in amelioration of DAL-induced oxidative stress." (PMID 27486371, 2015). "Formation of cell-derived singlet oxygen required an initial local inactivation of a few catalase molecules on the surface of tumor cells." (PMID 26225731, 2015). "In advanced stage IV, catalase levels in non-tumor tissues were increased whereas those in tumors were further reduced." (PMID 25361011, 2014). "Intriguingly, we have noticed that catalase levels in non-tumor tissues of the stage IV were increased." (PMID 25361011, 2014). "Here, we used each patient's own non-tumor tissue (N) as a control for catalase expression in tumor (T), calculating a T/N ratio of catalase expression for each patient." (PMID 25361011, 2014). "MnSOD expression also showed a reduction in tumor tissues although this difference was weaker than catalase." (PMID 25361011, 2014). "Conversely, catalase expression was much lower in tumor tissues than in non-tumor tissues (**p<0.01; Wilcoxon's signed-rank test)." (PMID 25361011, 2014). "In contrast, decrease in catalase level in tumor tissue was especially marked in the stage IV specimens." (PMID 25361011, 2014). "A multivariate Cox proportional hazard regression analysis revealed that tumor differentiation (p=0.044) and catalase expression (p=0.035) were independent prognostic factors for the overall survival of HCC patients." (PMID 25361011, 2014). "Among 50 paired samples from HCCs patients, 45 (90%) tumor samples showed much higher levels of HBx protein than surrounding non-tumor samples; conversely, catalase expression level was significantly lower in most tumor samples (78%)." (PMID 25361011, 2014). "The results of the present study showed that the levels of MDA and the activities of the enzymes SOD and CAT were found to be significantly changed in tumor bearing mice compared to the healthy controls." (PMID 24175309, 2013). "Further detailed study of the molecular mechanism of Arg transport in neoplasm cells is warranted since many unresolved issues remain, such as the regulation and distribution of CAT expression in cancer cells." (PMID 24040099, 2013). "The overexpression of catalase that converts hydrogen peroxide to water and Ebselen, a glutathione peroxidase mimic inhibited cell transformation and tumor formation." (PMID 23437041, 2013). "We found that overexpression of catalase inhibited tumor spheroid formation 4-OH-E2-transformed MCF-10A cells." (PMID 23437041, 2013).
tumor (continued). "Increased MDA levels and SOD and CAT enzymes activities were found in the liver homogenates of tumor bearing mice after alone treatment with BLM compared to the control mice." (PMID 24175309, 2013). "ROS detoxifying enzymes (e.g. catalase, peroxiredoxin 6, superoxide dismutase) were considerably upregulated in all tumor types." (PMID 22693581, 2012). "Scavenging of H2O2 in tumor cells either treated with exogenous catalase or expressing transfected catalase inhibits cell proliferation." (PMID 22970236, 2012). "lipid peroxidation, reduced glutathione level (GSH), activities of glutathione-S-transferase (GST), superoxide dismutase (SOD) and catalase (CAT) in tumor bearing mice." (PMID 22319252, 2011). "Targeting catalase within mitochondria of tumor cells and tumor stromal cells suppresses ROS-driven tumor progression and metastasis." (PMID 21605372, 2011). "For example, there are numerous papers directly showing that local or systemic administration of purified anti-oxidant proteins (that is, catalase or SOD) is sufficient to block tumor recurrence and distant metastasis in multiple cancer models." (PMID 21605374, 2011). "The results of our study indicate that the enzymatic GOX/CAT system is an attractive alternative technique for in vitro investigation of tumor hypoxia." (PMID 21477371, 2011). "The extract also restored the hepatic lipid peroxidation and antioxidant enzymes such as CAT in tumor-bearing mice to near normal levels." (PMID 21607054, 2011). "Remarkably, MMTV-PyMT mice expressing mito-catalase showed a significant reduction in tumor grade (from high-grade to low-grade), and a dramatic reduction in lung metastatic tumor burden (>12-fold)." (PMID 21605374, 2011). "Production of ROS results in apoptosis and/or necrosis and can be used for selective targeting of tumor cells which possess higher oxidative stress level and display alteration of antioxidant enzymes (catalase, SOD) as compared to normal cells." (PMID 20184758, 2010). "The ROS levels were significantly higher in the tumor cell lines that possessed low catalase activity." (PMID 21108789, 2010). "Patients with malignant tumors also displayed higher plasma levels of both PADI4 and cAT than patients with benign and non-tumor inflammations." (PMID 19183436, 2009). "Because the cAT content in the plasma declined after tumor excision surgery and was generally associated with PADI4 levels in the blood, we propose that the high cAT levels observed in the blood was due to citrullination of PADI4 in tumor tissues." (PMID 19183436, 2009). "Typically, antioxidative enzymes like glutathione peroxidase, catalase or superoxide dismutase are downregulated in tumor cells." (PMID 19508729, 2009). "Plasma levels of cAT and PADI4 in patients with these malignancies were significantly associated with levels of known tumor markers." (PMID 19183436, 2009). "Since we previously detected citrullination and subsequent inactivation of antithrombin in the plasma of RA patients, we also measured levels of citrullinated antithrombin (cAT) in the blood of patients containing various tumor types." (PMID 19183436, 2009). "Previous studies have shown decreased catalase activity in the liver and kidneys of tumour-bearing rats." (PMID 18226207, 2008). "The addition of SOD and/or catalase to ROS-exposed MEC decreased the enhanced tumour cell adhesion significantly." (PMID 17088916, 2006). "Although the catalase activity remained more or less unchanged, the GPx activity also increased to some extent in tumor cells following CuNG treatment of EAC/Dox bearing mice (data not shown)." (PMID 17107616, 2006). "We then compared the antioxidative enzyme activities such as those of SOD, glutathione peroxidase and catalase in the serum or tumour tissues after oral administration of oxykine, gliadin or melon-SOD." (PMID 16508635, 2006). "Addition of the antioxidant enzymes superoxide dismutase or catalase significantly decreased tumour cell adhesion (P<0.01)." (PMID 17088916, 2006).
tumor (continued). "The activity of enzymatic defences against free radical attack including superoxide dismutase (SOD), catalase, glutathione peroxidase and glutathione reductase have been compared in some experimental animal tumours with the corresponding normal mouse tissues." (PMID 6860548, 1983). "Antioxidant enzymes such as superoxide dismutase (SOD) and catalase (CAT) may also exhibit reduced activity in tumor tissue." (PMID 40864821, 2025). "CAT not only alleviates the hypoxic tumor microenvironment but also consumes the produced H2O2." (PMID 40358287, 2025). "Furthermore, CAT-catalyzed oxygen generation from endogenous H2O2 alleviated tumor hypoxia, significantly enhancing SDT efficacy." (PMID 40869210, 2025). "Given its role in maintaining redox balance, CAT upregulation in LSCC may contribute to tumor adaptation by neutralizing oxidative stress, thereby supporting cancer cell survival and progression." (PMID 40149643, 2025). "The cytoprotective and antioxidant genes, such as GPX1, CAT, and SOD2, are some examples of NRF2-regulated genes that could be implicated in tumor progression, metastasis, and resistance to chemotherapy." (PMID 40565143, 2025). "In another study, a biodegradable nanoplatform named CSI is developed by encapsulating catalase (CAT) within silica nanoparticles (CAT@SiO2) to alleviate tumor hypoxia, followed by loading these particles with the sonosensitizer indocyanine green (ICG) in macrophage‐derived exosomes." (PMID 40007074, 2025). "Furthermore, in combination with HFMF,cerium oxide plays a crucial role in tumor retention by acting asa catalase (CAT)-like agent." (PMID 39739571, 2025). "This review highlights two distinct recycling branches: 40S subunit recycling, mediated by the USP10‐G3BP1 complex and linked to mitochondrial dynamics, and 60S subunit disassembly via RQC/CAT‐tailing, influencing cellular stress, protein aggregation, and tumor progression." (PMID 40785597, 2025). "The metabolic metabolites of Lactobacillus, such as antioxidants such as glutathione, superoxide dismutase and catalase, have unique efficacy in alleviating intestinal inflammation and inhibiting the expression of tumor-specific proteins and polyamine components." (PMID 41019527, 2025). "Additionally, the catalase (CAT)-like activity facilitates the generation of O2 to alleviate the hypoxic microenvironment and promote the sono-activable effects on tumor cell death." (PMID 40610512, 2025). "Catalase delivery for inhibiting ROS-mediated tissue injury and tumor metastasis." (PMID 37469162, 2024). "Additionally, by injecting four groups of cells (1 × 105/50 μL) into the tail vein and imaged after 50 days, we found that overexpression of Parkin inhibited the lung metastasis of tumor cells in mice, while overexpression of Catalase promoted lung metastasis." (PMID 38424181, 2024). "Recently, a synthetic biology approach 115 was proposed to construct a transdermal theranostic microneedle patch integrated with 5-ALA and catalase coloaded tumor acidity-responsive copper-doped calcium phosphate nanoparticles by maximizing the enrichment of intratumoral protoporphyrin IX." (PMID 38164160, 2024). "At the tumor site, highly expressed glutathione triggered the biodegradation of CSIs, and the catalase that was released catalyzed the production of O2 from H2O2 in the tumor, thus alleviating the hypoxic microenvironment and improving the efficiency of sonodynamic therapy." (PMID 38890722, 2024). "CASP3, SRC, ESR1, JAK2, PRKACA, HSPA8 and CAT exhibited stronger interactions with other factors, suggesting that they may be the key targets for tumor treatment." (PMID 38675723, 2024). "Targeting CAT could disrupt H2O2-mediated tumor-promoting signaling pathways that drive cancer cell metabolism and proliferation and increase the susceptibility of PCa cells to oxidative stress-induced cell death." (PMID 39594482, 2024).